RN7SL462P (RNA, 7SL, cytoplasmic 462, pseudogene)
Gene: Miscellaneous RNA gene on chromosome 9 (61,427,617 to 61,427,877, reverse strand). Ensembl gene ENSG00000276522.
Homologues: Orthologues: chimpanzee Metazoa_SRP (99% identical). Paralogues in human: RN7SL343P (100% identical), RN7SL640P (100% identical), RN7SL422P (99% identical), RN7SL2 (82% identical), RN7SL3 (82% identical), RN7SL1 (81% identical), RN7SL464P (80% identical), RN7SL607P (79% identical), RN7SL597P (79% identical), RN7SL804P (79% identical), RN7SL655P (79% identical), RN7SL543P (78% identical), and 705 more.